DAW1 (dynein assembly factor with WD repeats 1)
Description:
Required for axonemal dynein assembly and ciliary motility in ciliated organs, including Kupffer's vesicle, during embryogenesis. Facilitates the onset of robust cilia motility during development.
Synonyms: ODA16; WDR69; FLJ25955; DNAAF18; CILD52
Tractability: Antibody: its Gene Ontology location is reachable by antibodies, with medium confidence; the Human Protein Atlas places it where antibodies can reach.
Gene: Protein-coding gene on chromosome 2 (227,870,931 to 227,924,344, forward strand). Ensembl gene ENSG00000123977.
Subcellular location: Cytoplasm, cytoskeleton, flagellum basal body; Cytoplasm, cytoskeleton, flagellum axoneme
Subcellular location (Human Protein Atlas): End piece; Mid piece; Principal piece; Plasma membrane
Gene Ontology:
Molecular function: protein binding; ubiquitin-like ligase-substrate adaptor activity
Biological process: intraciliary transport; outer dynein arm assembly; protein polyubiquitination; axonemal dynein complex assembly; determination of left/right symmetry; heart development
Cellular component: ciliary basal body; cilium; SCF ubiquitin ligase complex
Genetic constraint (gnomAD): Loss-of-function variants: 38 observed, 43.97 expected, observed/expected ratio (o/e) 0.86, 90% interval 0.67 to 1.13. The upper end of that interval is the gene's LOEUF score, 1.13, which puts it in group 4 of 6, group 1 being the genes least tolerant of losing a copy. Missense variants: 442 observed, 451.61 expected, observed/expected ratio (o/e) 0.98, 90% interval 0.9 to 1.06. Synonymous variants: 172 observed, 165.89 expected, observed/expected ratio (o/e) 1.04, 90% interval 0.92 to 1.18.
Gene-disease validity (ClinGen):
ClinGen rates the evidence that DAW1 causes each of these diseases.
visceral heterotaxy (autosomal recessive): Moderate. A rare, genetic disorder in which symptoms are generally secondary to the abnormal location of the organs within the thoracic, abdominal, or peritoneal cavities.
primary ciliary dyskinesia (autosomal recessive): Limited. A rare, genetically heterogeneous, primarily respiratory disorder characterized by chronic upper and lower respiratory tract disease.
Homologues: Orthologues: chimpanzee DAW1 (99% identical), macaque DAW1 (96% identical), pig DAW1 (92% identical), mouse Daw1 (90% identical), dog DAW1 (87% identical), guinea pig DAW1 (87% identical), rat Daw1 (86% identical), tropical clawed frog daw1 (76% identical), zebrafish daw1 (72% identical). Paralogues in human: WDR88 (24% identical), MAPKBP1 (21% identical), WDR62 (20% identical), TEP1 (20% identical), PAFAH1B1 (19% identical), AHI1 (18% identical), WDR27 (18% identical), NWD1 (17% identical), WDR7 (17% identical), WDR81 (17% identical), POC1A (17% identical), POC1B (16% identical), and 14 more.
Diseases named in the same sentence as DAW1 in open-access papers:
DAW1 is named in the same sentence as 10 diseases in open-access papers, as found by Europe PMC text mining. Sharing a sentence is not in itself a finding about the gene and the disease. The quoted sentences say what the papers report.
congenital heart disease (1 paper, 2026). A heart disease that is present at birth. "Here, we identify compound heterozygous variants in DAW1, a dynein arm assembly factor, in a proband with HTX and complex congenital heart disease but no clinical signs of PCD." (PMID 41727625, 2026).
COVID-19 (1 paper, 2024). A disease caused by infection with severe acute respiratory syndrome coronavirus 2. "DAW1, ESF1, KCTD2, USP45, PNMA8A, SYNDIG1L, and CC2D2B are novel genes/proteins that may be linked to COVID-19." (PMID 38674024, 2024).
diabetic cardiomyopathy (1 paper, 2019). Diabetic cardiomyopathy is a disorder of the heart muscle in people with diabetes. "This study profiles differently expressed lncRNAs in type 2 mice with and without early diabetic cardiomyopathy and identifies BC038927, G730013B05Rik, 2700054A10Rik, AK089884, and Daw1 as the core lncRNA with high significance in diabetic cardiomyopathy." (PMID 31653946, 2019).
male infertility (1 paper, 2024). The inability of the male to effect fertilization of an ovum after a specified period of unprotected intercourse. "Lately, several genes have been reported to be associated with laterality defects, male infertility, and mild variable respiratory phenotypes such as CCDC11/CFAP53, ENKUR, WDR16/CFAP52, DAW1, and MNS1." (PMID 38920647, 2024).
DAW1 also shares sentences with these, for which no sentence is quoted: primary ciliary dyskinesia (2 papers); tumor (2); ciliopathies (1); glioma (1); hepatocellular carcinoma (1); tauopathy (1).